EGFR (epidermal growth factor receptor)
Diseases named in the same sentence as EGFR in open-access papers (continued):
Sharing a sentence is not in itself a finding about the gene and the disease.
bladder tumors (continued). "Cell binding studies were performed with either Cy5.5-N24-EGF, Cy5.5-N40 or PBS by treating canine cell lines isolated from spontaneous canine bladder tumors that expressed low (K9TCC-Original) and high EGFR (K9TCC-SH), respectively." (PMID 36082359, 2022). "In vivo studies have shown that the inhibition of EGFR, VEGF, and mTOR suppresses bladder tumour growth." (PMID 32872665, 2020). "Molecular classification of bladder tumors into luminal and basal subtypes has refined therapeutic strategies: FGFR inhibitors for luminal-papillary tumors, EGFR-targeted and chemotherapy approaches for basal/squamous cases, and immune-checkpoint inhibitors guided by immune-infiltration profiles." (PMID 40698358, 2025). "Moreover, combined EGFR and HER2 targeted NIR-PIT inhibited tumor growth significantly in a xenograft bladder tumor model." (PMID 36405499, 2021). "However, no significant changes in the expression of EGFR were observed in bladder tumors compared to their normal tissue counterparts." (PMID 36471329, 2022). "Likewise, suppressing cellular proliferation with epidermal growth factor receptor (EGFR) inhibitors has been used pre-clinically to reduce basal-like muscle invasive bladder tumor growth, although, the EGFR inhibitors did not have the same efficacy in non-basal-like tumors." (PMID 32822399, 2020).
Hyperglycemia (44 papers, 2012 to 2025). An increased concentration of glucose in the blood. "Angiotensin II and ROS reinforce one another and together with hyperglycemia activate epidermal growth factor receptor (EGFR)/Src/TGF-β1 signaling, driving ECM deposition and glomerulosclerosis." (PMID 40725208, 2025). "The inhibition of PDX-1 and EGFR signaling in the pancreas by chronic hyperglycemia results in impaired insulin synthesis and secretion and β-cell proliferation." (PMID 41189666, 2025). "Diabetic wounds remain trapped in a hyper-inflammatory state because persistent hyperglycaemia stimulates keratinocyte IL-8 production via an EGFR–ERK pathway, increasing neutrophil recruitment and activation." (PMID 41614737, 2025). "This interaction plays a crucial part in the hyperglycemia-induced injury and fibrosis of the proximal tubules by retaining chronic activation of the EGFR/TGF-β/Smad3 pathway." (PMID 39234105, 2024). "A study showed that EGFR/PI3K/RhoA signaling is essential for hyperglycemia-induced SREBP-1 activation which then results in TGF- β1 upregulation." (PMID 39234105, 2024). "Hyperglycemia also increases the ROS that disturbs the EGFR pathway, resulting in delayed corneal epithelial wound healing." (PMID 37374078, 2023). "The composition of growth media for the enteroid culture contains the epidermal growth factor (EGF), therefore mimicking in vivo conditions where hyperglycemia and EGFR activation coexist." (PMID 37637953, 2023). "The fact that EGFR is highly ranked in both lists suggests its involvement in multiple regulatory mechanisms or pathways affected by hyperglycemia." (PMID 37374078, 2023). "In the present study, we compared FBG levels and EGFR expression in different OSCC populations to explore the effects of hyperglycemia and metformin on EGFR expression and found that the expression of EGFR in OSCC is related to FBG fluctuations." (PMID 35222283, 2022). "These receptors have a methionine gatekeeper in their kinase domains, and are related to hyperglycemia in other clinical trials of EGFR TKI, such as Co-1686." (PMID 33986687, 2021). "EGFR inhibition with gefitinib decreased hyperglycemia-induced cardiac remodeling by preventing oxidative stress-induced changes in the diabetic heart." (PMID 34408653, 2021). "For example, in the diabetic mesenteric vascular bed, hyperglycemia-induced upregulation of Akt signaling was prevented by lapatinib, a dual inhibitor of EGFR and ErbB2." (PMID 34408653, 2021). "We suggest that hyperglycaemia enhances EGF signalling via EGFR–ErbB2 heterodimers, which seem to be the starting point of the pathological signalling cascade." (PMID 32548701, 2020). "The impact of hyperglycaemia on EGFR-induced signalling and SRF transcriptional activity and the underlying mechanisms were investigated at the cellular level." (PMID 32548701, 2020). "Emerging evidence suggests that dysregulation of the epidermal growth factor (EGF) receptor (EGFR or ErbB) family of receptor tyrosine kinases (RTKs) appears important in mediating hyperglycemia-induced vascular dysfunction." (PMID 26536590, 2015). "Furthermore, alterations in the epidermal growth factor receptor (EGFR) signalling pathway due to hyperglycaemia contribute to delayed wound healing, complicating treatment approaches." (PMID 39797325, 2025). "This condition of hyperglycemia can also be a consequence of the disruption of key gluconeogenesis enzymes, such as pyruvate carboxylase, phosphoenolpyruvate carboxykinase, and glucose-6-phosphatase, as a result of the decreased EGFR activity." (PMID 38067203, 2023). "Hyperglycemia independently or jointly promotes tumor progression within the tumor microenvironment, by activating the abnormally upregulated expression of epidermal growth factor and its receptor EGFR in cancer." (PMID 35461311, 2022).
Hyperglycemia (continued). "Interestingly, an enhanced EGFR phosphorylation has been identified in diabetic vascular tissues collected from the constructed animal models and in human cells under conditions mimicking hyperglycemia." (PMID 38027164, 2023). "The results indicated that HG could induce the DN phenotypes in SV40 cells via EGFR activation, both EGFR inhibitor and ROS scavenger could prevent the cell damages, suggesting that EGFR and ROS play pivot roles in mediating hyperglycemia-induced renal pathogenesis." (PMID 28427241, 2017). "In addition, considering that some of the EGFR inhibitors induced hyperglycemia in the clinic, which was possibly through inhibition of the INSR and IGF1R kinases, we also tested this drug in parallel with AZD9291 in the INSR and IGF1R transformed isogenic BaF3 cells." (PMID 28407693, 2017). "Notably SN strongly stimulated AKT activation and EGFR activation under hyperglycemia." (PMID 24086307, 2013). "EGFR signalling and SRF activation are redox-sensitive offering an explanation for the potentiating effect of hyperglycaemia." (PMID 32548701, 2020). "In conclusion, knocking down EGFR and AKT prevented the HG-induced ER stress, pro-apoptosis, and fibrosis, indicating that the EGFR/AKT/ROS/ER stress pathway contributes to the hyperglycemia-induced renal cell damages." (PMID 28427241, 2017). "Previous studies have suggested that PKC-α mediates epidermal growth factor receptor (EGFR) ubiquitination in podocytes, cell surface endocytosis, and subsequent extracellular signal-regulated kinase (ERK) activation during hyperglycemia, leading to podocyte injury." (PMID 40230860, 2025). "Moreover, hyperglycemia fuels the proliferation of PC cells through the induction of EGF expression and EGFR activation." (PMID 38523554, 2024). "Hyperglycemia-mediated decrease in FOXO3A phosphorylation and increased total FOXO3A levels could be reversed upon lapatinib treatment (a dual inhibitor of EGFR and ErbB2 receptors)." (PMID 34408653, 2021). "For example, in mesangial cells exposed to hyperglycemia, general inhibition of matrix metalloproteases, MMPs, (known to be involved in EGF-like ligand shedding) or specifically of HB-EGF ligand inhibited the activation of both, EGFR and downstream AKT signaling." (PMID 39234105, 2024). "Chronic treatment with AG825 or AG1478, selective inhibitors of erbB2 and EGFR respectively, did not affect hyperglycemia but led to an exacerbation whereas acute administration of the EGFR ligand, epidermal growth factor (EGF), led to an improvement in cardiac recovery in diabetic hearts." (PMID 22720029, 2012). "In addition, a rat oral glucose tolerance test revealed that treatment with high drug doses (50 mg/kg) of DY3002 did not result in hyperglycemia, suggesting a reduction of side effects in NSCLC patients will be achievable relative to established EGFR inhibitors." (PMID 27827863, 2016).
mesothelioma (44 papers, 1990 to 2025). A usually malignant and aggressive neoplasm of the mesothelium which is often associated with exposure to asbestos. "EGFR expression is implicated in PM oncogenesis, and treatment of EGFR expressing mesothelioma cell lines with gefitinib caused significant growth inhibition." (PMID 40361508, 2025). "Here we report the first identification of EGFR activating mutations in mesothelioma, as well as, the updated clinical outcome." (PMID 20942962, 2010). "Therefore, identification of surrogate markers that can predict response to CRS/IPHC and lead to novel therapeutic targets in mesothelioma prompted the pursuit of EGFR mutations." (PMID 20942962, 2010). "The identification of EGFR mutations in peritoneal mesothelioma expands the spectrum of cancers with EGFR pathway perturbations and provides the first evidence of function EGFR mutations in mesothelioma." (PMID 20942962, 2010). "Therefore it is unknown if EGFR mutations occur in pleural mesothelioma or if a subset of mesothelioma patients might benefit from EGFR-TKI therapy and further investigation for perturbations in the EGFR pathway in pleural mesothelioma is warranted." (PMID 20942962, 2010). "EGFR inhibitors have been investigated in MPM due to the frequent overexpression of EGFR in mesothelioma tumors, reported in approximately 60–70% of cases." (PMID 40647443, 2025). "All together these results suggest that progranulin modulates EGFR activation in mesothelioma cells." (PMID 36471440, 2022). "The nanoconstruct targeted EGFR (a mesothelioma overexpression receptor), and the main targets were genes involved in the progression of this cancer, e.g., BCL2, CDK1, and JUN." (PMID 35326459, 2022). "Epidermal growth factor receptor (EGFR) is one of the main targets in mesothelioma treatment strategies due to its overexpression reaching 75% in MPM patients." (PMID 34361048, 2021). "Although mesothelioma cells are known to overexpress EGFR, clinical trials of EGFR inhibitors for pleural mesothelioma have not proven their effectiveness." (PMID 33319489, 2021). "A high EGFR expression was present in all mesothelioma cell lines evaluated and mAb806 binding present in all cell lines, except NCIH-2452." (PMID 33023139, 2020). "EGFR and mAb806 epitope expressions in mesothelioma cell lines were evaluated using an array of binding assays, and the in vitro cell effects of ABT-414 and ABBV-322 were determined." (PMID 33023139, 2020). "Strong EGFR immunoreactivity, when measured by immunohistochemical (IHC) staining using the pan-EGFR antibody mAb528, was present in all four mesothelioma cell lines, as previously reported, with median H scores of 150, 210, 125 and 230, respectively." (PMID 33023139, 2020). "Whereas growth in EGFR-expressing mesothelioma cell lines is significantly deterred by EGFR small molecule inhibitors, clinical evaluations of gefitinib and erlotinib were dismal in MPM patients." (PMID 29342862, 2018). "Various studies have reported on the expression and activation of RTKs in mesothelioma, including EGFR, MET, IGFR, FGFR1, and VEGFR." (PMID 29755689, 2018). "Similar results were shown using Gefitinib and Cetuximab, which strongly indicates that high EGFR expression cannot be used to predict response to EGFR inhibitors in patients with mesothelioma." (PMID 29848954, 2018). "In support of this observation, various mesothelioma cell lines tested showed decreased ERK5 phosphorylation when treated with EGFR phosphorylation inhibitor (AG1478)." (PMID 29416614, 2018). "Epidermal growth factor receptor is a key driver of cell proliferation, which was detected in all the cell lines and in the majority of mesothelioma specimens in the present study, as well as in previous studies." (PMID 21970874, 2011). "In that same study, elevated serum and tissue HER1 was significantly associated with advanced disease stage, suggesting an important role of EGFR over-expression in mesothelioma." (PMID 21464917, 2011).
mesothelioma (continued). "Here we present the mutant EGFR activating potential and the matured survival data of the EGFR mutant(mut+) relative to wild type EGFR(mut-) mesothelioma." (PMID 20942962, 2010). "A number of selective inhibitors of the TEAD family members are in development and have been shown to disrupt YAP1/WWTR1/TEAD-dependent transcription, affect the viability of NF2 mutant mesothelioma models, and to enhance the efficacy of EGFR inhibitors in EGFR mutant lung cancer." (PMID 38658677, 2024). "However, several receptor tyrosine kinase pathways have been shown to be triggered in mesothelioma, including the epidermal growth factor receptor (EGFR), insulin-like growth factor receptor (IGFR), and c-Met, all of which activate Ras signaling." (PMID 36831074, 2023). "Additionally, the nanocells are coated with EGFR-specific antibodies on their surface to target the tumor overexpressing EGFR on mesothelioma cells." (PMID 38068916, 2023). "Notably, as in MSTO-211H, EGFR inhibition attenuated the phosphorylation of EphA2 on S897 in NCI-H2052 cells as well, suggesting a modulation of EphA2 activity by EGFR in mesothelioma cells." (PMID 36471440, 2022). "However, several receptor tyrosine kinase pathways have been shown to be activated in mesothelioma including the epidermal growth factor receptor (EGFR), insulin-like growth factor receptor (IGFR), and c-Met90–92, all of which activate Ras signaling." (PMID 35654808, 2022). "Based on these results, we investigated whether endogenous progranulin might affect EGFR activation in mesothelioma cells." (PMID 36471440, 2022). "Moreover, miR-16-based mimics that target epidermal growth factor receptor (EGFR) have shown acceptable safety and preliminary activity in a phase I study in 26 mesothelioma patients." (PMID 34226685, 2021). "Specific inhibition of VEGFR, FGFR1, MET and/or EGFR suppressed mesothelioma cell growth in vitro." (PMID 29755689, 2018). "In addition, because EGFR modulates EphA2 phosphorylation at Ser897 in mesothelioma cells, we can also hypothesize that EGFR could promote RYK phosphorylation indirectly by modulating EphA2 activity." (PMID 36980592, 2023). "In summary, we found that the transcript levels of EGFR and MMP1 were downregulated, while EPHA5 and PARK2 were upregulated in response to YB‐1 knockdown using both siRNAs in mesothelioma cells." (PMID 36550787, 2024). "In our examples, tumor-selective mRNAs in the HNCs (EGFR, CDH1) were stable, however, mesothelioma-selective mRNAs (i.e., mesothelin and WT1) were reduced." (PMID 38744944, 2024). "By contrast, the phospho-RTK array data suggested that EGFR, RYK and EphA7 are activated upon progranulin stimulation of mesothelioma cells." (PMID 36471440, 2022). "EGFR and mAb806 epitope expression were determined in MSTO-211H, NCIH-28, NCIH-2052 and NCIH-2452 mesothelioma cell lines in a series of binding assays by immunohistochemistry, Fluorescence-activated cell sorting (FACS) and Western blot analysis." (PMID 33023139, 2020). "14R091 is a mesothelioma PDX model of the epithelioid subtype, which has high EGFR and mAb806 epitope expression by IHC (EGFR: H score > 200 and mAb806: H score 170) but lacks true EGFR amplification on Fluorescence in situ hybridization (FISH)." (PMID 33023139, 2020). "Lately, vascular endothelial growth factor receptor (VEGFR) and the epidermal growth factor receptor (EGFR) have been reported as potential targets for anticancer therapies; its overexpression in mesothelioma has been also reported." (PMID 30501113, 2018). "Recently, it was shown that the combination of rapamycin or PI3K/mTOR inhibitors and one specific RTK inhibitor (EGFR, MET or IGF1R inhibitor) suppressed adverse AKT activation and hampered mesothelioma cell growth in vitro and in MPM xenografts." (PMID 29755689, 2018). "Mesothelioma often up-regulated expression of vascular endothelial growth factor (VEGF), epidermal growth factor (EGF) and the corresponding receptors (VEGFR, EGFR)." (PMID 26191485, 2015).
mesothelioma (continued). "It is tempting to hypothesize that, in mesothelioma, EGFR could be involved in progranulin-stimulated RYK tyrosine-phosphorylation and that progranulin signaling might depend on EGFR and RYK physical and functional interactions." (PMID 36980592, 2023). "Recently, we have demonstrated that in mesothelioma cells, EphA2 is not the major progranulin signaling receptor and progranulin action is instead mediated by EGFR and RYK, a co-receptor of the Wnt pathway." (PMID 36980592, 2023). "Taken together, these results suggest that progranulin might sustain the activation of multiple RTKs in mesothelioma cells and signaling triggered by progranulin to AKT and MAPK activation might rely on EGFR and RYK in mesothelioma cells." (PMID 36471440, 2022). "In particular, we found proteins involved in the regulation of pathways aberrantly activated in mesothelioma, such as MAPK, PI3K-Akt and mTOR signalling pathways, as well as the EGFR, Hippo, epithelial to mesenchymal transition and NF-kappa B signalling pathways." (PMID 35987988, 2022). "In the cell binding assay, we used the A431 cell line that overexpresses EGFR on their surface (2 × 106 receptors by cell), we found an elevated percentage of RIC binding efficiency in the cell line MSTO-211H (biphasic mesothelioma cells), with less expression of EGFR (34 vs. 21%)." (PMID 30501113, 2018). "Taken together these findings suggest that in mesothelioma cell lines, XMD8-92-induced ERK5 inhibition could in part be mediated by EGFR." (PMID 29416614, 2018). "Although clinical trial results for EGFR inhibitors in mesothelioma have not been released, concurrent inhibition of various activated RTKs with pro-apoptotic and anti-proliferative effects in mesothelioma cell lines have paved the way to such trials." (PMID 28191281, 2016). "Moreover, despite a high expression of EGFR or VEGF in mesothelioma, none of the single-agent therapies with (multi)targeted tyrosine kinase inhibitors have been successful." (PMID 36657447, 2023). "Based on these published data, we can therefore speculate that the presence or absence of merlin in mesothelioma cells might determine different EGFR/RYK endocytosis/sorting, which could modulate the intensity of progranulin-dependent downstream signaling." (PMID 36471440, 2022). "However, our results indicate that EphA2 is not the major functional receptor for progranulin in mesothelioma cells, where progranulin activates a complex signaling network including EGFR and RYK." (PMID 36471440, 2022). "Mesothelioma cells transfected with the novel plasmid pMRX‐IP‐GFP‐LC3‐RFP‐LC3ΔG, which was developed for the quantitative and statistical estimation of macroautophagy, showed enhanced macroautophagy upon treatment with VER‐155008 and gefitinib which is an EGFR‐tyrosine kinase inhibitor." (PMID 33319489, 2021). "Thus, coexpression of EGFR and TGF-alpha is observed on two mesothelioma cell lines." (PMID 7947089, 1994). "Since we have demonstrated that progranulin might activate EGFR and RYK in mesothelioma and considering that both EGFR and RYK might directly or indirectly modulate FAK activity, we asked whether progranulin-dependent regulation of FAK activity was mediated by EGFR and/or RYK." (PMID 36471440, 2022). "However, the contribution of EphA2 activation is not clearly defined in mesothelioma cells, where we identified by RTK arrays that progranulin promoted tyrosine-phosphorylation of EGFR and RYK." (PMID 36980592, 2023). "Molecular targeting agents that inhibit EGF/EGFR or VEGF/VEGFR pathway such as erlotinib, gefinitib and bevacizumab however failed to produce clinical benefits, but an inhibitor to block the HGF/c-Met pathway has not yet been examined for the efficacy to mesothelioma." (PMID 26191485, 2015).